HDAC1 (histone deacetylase 1)
Diseases named in the same sentence as HDAC1 in open-access papers (continued):
Sharing a sentence is not in itself a finding about the gene and the disease.
bladder cancer (16 papers, 2011 to 2026). "Although pathological examination revealed that HDAC1 was significantly associated with high bladder cancer tumor grades, whether maspin acts as an HDAC1 inhibitor in bladder carcinoma cells remains unclear." (PMID 31861435, 2019). "The utilization of HDAC1 as diagnostic biomarker and druggable target for bladder cancer is further reinforced by the prominent elevation of its mRNA contents in clinically cancerous tissue biopsies versus healthy tissue biopsies, recently reported in a study of 88 patients." (PMID 30875794, 2019). "HDAC1 (FC = 1.63-fold, q = 0,082) is overexpressed in many cancers such as colon and testis and its overexpression was associated with high-grade tumors and poor prognosis in bladder cancer." (PMID 30419021, 2018). "Members of the HDAC family exhibit subtype-specific abnormalities in bladder cancer: Class I HDACs (HDAC1, 2, 3) are overexpressed in 40%–59% of bladder cancers." (PMID 41438986, 2025). "Lastly, oncogenic metabolic hubs in bladder cancer were negatively correlated with USF2-NuRD complex scores whereas positively correlated with HDAC1/2 target scores." (PMID 40626022, 2025). "Compared to TRT-HU-1 cells, an immortalized healthy bladder epithelial cells, HDAC1/2/3 are all overexpressed in bladder cancer cells." (PMID 37479885, 2023). "The bladder cancer cell line-dependent regulation of HDAC1 gene (and its cognate protein product) seems to further support the functional interactions of certain tumorigenic determinants with HDAC transcription machineries, in specific settings of malignancy." (PMID 30875794, 2019). "In accordance, in a small-scale study, HDAC1 mRNA was expressed at notably higher levels in urinary bladder cancer versus normal tissues, while the cognate protein was intensively compartmentalized in the tumorigenic, but not control, nuclei." (PMID 30875794, 2019). "HDAC1 activity assays also clearly indicated that maspin blocked the net HDAC1 activity in bladder carcinoma cells." (PMID 31861435, 2019). "Furthermore, some of our target genes with low mutation rates (HDAC1 and PARP1) are actually in clinical trials for bladder cancer." (PMID 35035776, 2022). "However, it is necessary to further investigate the precise mechanisms involved in the maspin/HDAC1 signaling axis in bladder cancer." (PMID 31861435, 2019). "Our results are the first to conclude that maspin may act as an HDAC1 inhibitor in bladder carcinoma cells in vitro and in vivo." (PMID 31861435, 2019). "To understand whether maspin serves as an endogenous inhibitor of HDAC1 activity in bladder carcinoma cells, we determined the modulation of maspin on HDAC1 activity and evaluated the downstream genes of maspin in RT-4, HT1376, or T24 cells." (PMID 31861435, 2019). "The maspin/HDAC1 signaling axis may represent the antitumor characteristics in human bladder carcinoma cells." (PMID 31861435, 2019). "Moreover, in bladder carcinoma cells, maspin modulated HDAC1 target genes, including cyclin D1, p21, MMP9, and vimentin." (PMID 31861435, 2019). "Similarly, exposure of bladder cancer-cell lines, with distinct HDAC1 and 2 expression profiles, to romidepsin resulted in significantly reduced proliferation, inhibition of clonogenic growth, disturbed cell-cycle progression, and induction of a mixed apoptotic and necrotic cell death." (PMID 30875794, 2019).
bladder cancer (continued). "Therefore, further investigation in precise mechanisms is warranted regarding whether the various subcellular distributions of maspin influence HDAC1 activity in bladder carcinoma cells." (PMID 31861435, 2019). "The HDAC1 isoenzyme is most pronounced in the cell lines MCF-7, BHY, and A427, whereas the urinary bladder cancer cell lines 5637, RT-4, and RT-112 show the lowest expression." (PMID 35008351, 2021). "Histone deacetylase 1 is expressed at higher levels in human bladder cancer compared to normal urothelium and its expression is also increased in the BBN mouse bladder cancer model." (PMID 22898175, 2012). "To validate the IHC result, we further determined expression of several HDACs, including HDAC4, HDAC1, and HDAC2, in the HTB4, HTB9, HTB2, HTB3, HTB5, HT1197 and HT1376 bladder cancer cells." (PMID 21507255, 2011). "Maspin acts as an HDAC1 inhibitor, which may modulate the p21, cyclin D1, MMP9, and vimentin expressions in bladder carcinoma cells." (PMID 31861435, 2019). "The fact that PRELP expression does not affect the expression levels of HDAC1, 2 is consistent with the view that the PRELP gene is activated following acetylation of H2BK5 and orchestrates the EMT program in bladder cancer cells." (PMID 36371227, 2022).
cervical carcinoma (16 papers, 2012 to 2025). A carcinoma arising from either the exocervical squamous epithelium or the endocervical glandular epithelium. "HDAC1/DNMT3A-containing complex is associated with the suppression of cancer stem cells in cervical cancer." (PMID 33671013, 2021). "However, a previous work revealed that HDAC1 is associated with the suppression of OCT4 in cervical cancer cells." (PMID 36566195, 2022). "In the end, our work showed that HDAC1 overexpression, via a unique Sp1/PP2A/pRb pathway, reduced proliferation and caused cervical cancer cells to undergo premature senescence." (PMID 40171441, 2025). "We have recently demonstrated that RFP interacts with HDAC1 and confers platinum-based drug resistance in cancer cell lines, including colon, breast, and cervical cancer cell lines, by decreasing TBP-2 expression." (PMID 23342271, 2012). "For cervical cancer cells, a high expression of HDAC1, HDAC2, and HDAC6 was found." (PMID 33634093, 2020). "Expression levels of HDAC1 and HDAC1 were increased in invasive HPV-positive cervical cancers compared normal epithelium and inversely correlated with p21CIP1/WAFf1 levels." (PMID 34361112, 2021). "For example, active participation of histone deacetylases (HDAC1, HDAC5 and HDAC6) in cervical cancer and significant degree made them vital for network maintenance." (PMID 31766427, 2019). "HDAC1 and HDAC6 are overexpressed in cervical cancer and contributes in cancer progression, metastasis and angiogenesis." (PMID 31766427, 2019). "In HeLa cervical cancer cells, SFN exerted negative effects on DNMT1 and HDAC1 activities." (PMID 30881375, 2019).
medulloblastoma (16 papers, 2011 to 2025). A malignant, invasive embryonal neoplasm arising from the cerebellum. "The interface between HDAC1 and one of the KBTBD4 β-propellers is stabilized by the medulloblastoma mutations, which insert a bulky side chain into the HDAC1 active site pocket." (PMID 39939763, 2025). "Certainly, the silencing of EIF4E3 and HDAC1 also represses the self-renewal capacity of medulloblastoma." (PMID 33066509, 2020). "In support of this, selective inhibition of HDAC1/2 results effective in inhibiting HH signaling and reducing tumor growth in Shh-dependent medulloblastoma mouse models through increased acetylation of Gli1 at Lys518." (PMID 31244888, 2019). "Here, the authors show that miR-584 acts as a therapeutic adjuvant as it sensitizes medulloblastoma to radiation and chemotherapy by targeting HDAC1 or eIF4E3 to enhance spindle defects and DNA damage." (PMID 30382096, 2018). "Meta-analyses of Gene expression omnibus data sets GSE2824541 (n = 64) and GSE8521742 (n = 763) data sets revealed that SH3CT2 expression was markedly lower, while expression of eIF4E3 and HDAC1 was higher in all sub-types of medulloblastoma." (PMID 30382096, 2018). "In medulloblastoma patients, reduced expression of miR-584-5p correlated with increased levels of HDAC1/eIF4E3." (PMID 30382096, 2018). "Another study reported that HDAC1 mRNA and protein levels were upregulated in mouse Ptch1+/− medulloblastoma." (PMID 23951168, 2013). "We found an increase in HDAC1 protein and mRNA levels in Smo/Smo cerebellum and Smo/Smo medulloblastoma as compared to wild-type cerebellum." (PMID 23951168, 2013). "HDAC1 was overexpressed in AT/RT compared to medulloblastoma." (PMID 34367950, 2021). "Together, these results suggest not only a complex regulation of various HDAC family members during medulloblastoma development but also that possibly not only HDAC1 but other HDACs, such as HDAC2, 3, or 6 might contribute to tumor development." (PMID 23951168, 2013). "Interestingly, a recent study found that Shh signaling, a major signaling pathway affected in medulloblastoma, is regulated by Gli acetylation and HDAC1." (PMID 21501498, 2011). "Second, we demonstrate that HDAC1/2 inhibitors can block the mutant KBTBD4–HDAC1 interface and proliferation of KBTBD4-mutant medulloblastoma cells." (PMID 39939763, 2025). "Mocetinostat (MGCD0103), an HDAC1/HDAC2 inhibitor, is found to target Gli1 acetylation to truncate SHH signaling in medulloblastoma cells." (PMID 31788346, 2019). "In a preclinical model of Shh-induced medulloblastoma, HDAC expression and activity of various HDAC family members, including HDAC1, 2, 3 and 6 were increased in tumors." (PMID 23951168, 2013). "The RNA-seq results from Fsmo;hGFAP-Cre medulloblastomas showed significant downregulation of histone acetyltransferases (HAT: Hat1 and Kat2a/GCN5), the histone deacetylase (HDAC) Hdac1, and the histone acetylation reader Brd2 between vehicle- and LDE-treated samples." (PMID 36688010, 2022). "In addition, the overexpression of miR-584-5p was identified to suppress the self-renewal of medulloblastoma cells owing to its ability to target EIF4E3 and HDAC1." (PMID 33066509, 2020). "Indeed, the use of the selective HDAC1/2 inhibitor mocetinostat inhibits HH signaling and reduces tumor growth in preclinical models of SHH-dependent medulloblastoma." (PMID 31244888, 2019). "MiR-584-5p overexpression or HDAC1/eIF4E3 silencing inhibited medulloblastoma stem cell self-renewal without affecting neural stem cell growth." (PMID 30382096, 2018). "In addition to HDAC1/2, the class II protein HDAC6 is found upregulated in medulloblastoma tumors, and its inhibition shows tumor suppressive effects in preclinical models of Shh-medulloblastoma." (PMID 31244888, 2019).
multiple myeloma (16 papers, 2008 to 2025). "Hsa_circ_0003489, by sponging miR-874-3p and increasing HDAC1 expression, stimulates autophagy and contributes to the drug resistance of myeloma cells." (PMID 36302650, 2023). "Mechanistically, elevated HDAC1 in the bortezomib-resistant myeloma cells deacetylates HP1γ at lysine 5 and consequently alleviates the ubiquitin-mediated protein degradation, as well as the aberrant DNA repair capacity." (PMID 36894562, 2023). "HDAC1 is a class I histone deacetylase gene and multiple myeloma patients with high protein levels of HDAC1 were shown to have poor progression-free and overall survival." (PMID 30854481, 2019). "Recently it has been shown that bortezomib, an agent approved for treatment of myeloma, induces apoptosis while decreasing HDAC1, 2 and 3 protein levels." (PMID 29795376, 2018). "Early targeting of this family of 11 enzymes(HDAC1–11) afforded a first generation of broadly acting inhibitorswith medicinal applications in oncology, specifically in cutaneousand peripheral T-cell lymphomas and in multiple myeloma." (PMID 39610753, 2024). "In the current study, we demonstrated that epigenetic regulation by HDACi in myeloma cells, especially isoform-selective inhibition of HDAC1, 2, 3, and 6 as well as broad inhibition induces an increase in CD26 transcripts by RT-PCR and CD26 protein expression by flow cytometry and IHC." (PMID 38284882, 2024). "Compared to that observed in the GEO data, HDAC1 expression changed in the myeloma cells." (PMID 33663586, 2021). "SAMSN1 regulates HDAC1 activity and is known as a tumor suppressor in multiple myeloma." (PMID 28714904, 2017). "Moreover, inhibition of HDAC1 is demonstrated to induce multiple myeloma cell death." (PMID 30854481, 2019). "Yet it was noteworthy that the protein levels of HDAC1 were not completely consistent with the mRNA levels in these myeloma cell lines." (PMID 34539893, 2021). "HDAC1 has been served as a target for cancer therapy, and small molecule HDAC inhibitors have been used in clinical treatment of patients with several types of cancer, such as T-cell lymphoma and multiple myeloma currently." (PMID 28424407, 2017).
asthma (13 papers, 2014 to 2025). "One single nucleotide polymorphism (SNP) in HDAC1 (rs1741981) is closely associated to asthma severity in a recessive model and increases the sensitivity to systemic corticosteroids treatment in asthmatic patients." (PMID 36311721, 2022). "A polymorphism in HDAC1 was shown to have a significant relationship with asthma severity and its presence was associated with lung function improvements in response to inhaled corticosteroid treatment in childhood asthmatics." (PMID 34968229, 2019). "Similarly, another study reported that the single nucleotide polymorphism (SNP) of HDAC1 (rs1741981) was significantly associated with asthma severity and response to corticosteroids." (PMID 35148729, 2022). "Moreover, defective HDAC2 activity is found in corticosteroid-insensitive severe asthma phenotypes and mice with HDAC1- deficient T-cells present increased eosinophil recruitment and Th2 cytokine production." (PMID 33673725, 2021). "Loss of HDAC1 (using the Cd4Cre delete strain) led to an increased inflammatory response in an in vivo allergic airway inflammation model and mice with HDAC1-deficient T cells displayed an increase in all clinical parameters of this Th2-type asthma model." (PMID 25333902, 2014). "HDAC1 induces histone deacetylation at the IL-12 promoter region, which inhibits IL-12 transcription in DCs and promotes the Th2 response in asthma." (PMID 41246337, 2025). "Recently, we have demonstrated that intranasal administrations of Pan-HDAC inhibitors, sodium butyrate and curcumin, which have effectively reduced asthma severity via HDAC1 inhibition in Ovalbumin induced mouse model." (PMID 37316684, 2023). "The differentially expressed genes (DEGs) analysis of 1,662 nasal−epithelium tissue samples and 572 DEGs from peripheral blood samples shows that HDAC1 is hub genes and serves an important role in the process of asthma." (PMID 36311721, 2022). "The results show that glucocorticoid treatment in patients with moderate asthma results in HDAC1 increase and restrain TNF-α and HAT and, therefore, suppresses Nf-kB and through that restrains IL-8." (PMID 33781317, 2021). "It is known that TGFB1 was a key cytokine that directs airway remodeling, and HDAC1 played a critical role in the pathogenesis of asthma." (PMID 34136532, 2021). "Collectively, these results indicate that RAGE may regulate HDAC1 expression in TDI-induced asthma via the PI3K/AKT pathway." (PMID 35148729, 2022). "In this study, we found for the first time that RAGE is a potential positive regulator of HDAC1 in a TDI-induced asthma model, and its role may be related to the PI3K/AKT signaling pathway." (PMID 35148729, 2022). "Subtype HDAC1 has been shown to play a vital role in asthma." (PMID 35148729, 2022). "HDAC1 expression is enhanced in patients with severe asthma compared with healthy volunteers." (PMID 36311721, 2022). "HDAC1 plays an important role in airway epithelial repair and remodeling and is found increased in severe asthma characterized by airway remodeling compared to mild asthma." (PMID 33673725, 2021). "Moreover, except for ATG3, HDAC1, and TGFB1, correlation analysis showed that the expression of the aging-related genes in peripheral blood of asthma patients was associated with pulmonary function parameters (FEV1%, FEV1, FVC, PEF, FEF75, FEF50, and FEF25)." (PMID 34136532, 2021). "In addition to differential HDAC expression, single nucleotide polymorphisms in both HDAC1 and HDAC2 have been observed in patients with asthma." (PMID 34968229, 2019). "The decreased expression of HDAC1 is also proposed to be a biomarker for severe asthma." (PMID 34968229, 2019). "The extent of HDAC1 reduction is speculative, since a slight increase in HDAC1 in patients suffering from severe asthma compared with regular patients has also been observed." (PMID 34968229, 2019). "HDAC1 expression was increased in patients with severe asthma compared with healthy volunteers." (PMID 27486985, 2016).
asthma (continued). "Selective targeting of HDAC1 may improve therapeutic effects of asthma." (PMID 36311721, 2022). "Additionally, murine models of asthma confirm the upregulation of HDAC1 could increase airway inflammation, Th2 cytokine level, IgE and goblet cell metaplasia dramatically." (PMID 36311721, 2022). "In summary, the expression of HDAC1 and HDAC2 in asthma is either slightly increased or decreased, and HAT activity is slightly increased." (PMID 34968229, 2019). "Additionally, a study found a small decrease in the expression of HDAC1 and HDAC2 in bronchial biopsies of asthma patients compared with healthy individuals." (PMID 34968229, 2019). "Moreover, expression of HDAC1 is upregulated by the stimulation of dermatophagoides pteronyssinus allergen (Der p 1) in peripheral blood mononuclear cells of patients with severe and non-severe asthma." (PMID 36311721, 2022).